CFAP54 (cilia and flagella associated protein 54)
Description:
Required for assembly and function of cilia and flagella.
Synonyms: C12orf55; C12orf63; FLJ31514; FLJ44112; CILD54; SPGF98
Tractability: Antibody: its Gene Ontology location is reachable by antibodies, with medium confidence.
Gene: Protein-coding gene on chromosome 12 (96,489,571 to 96,875,555, forward strand). Ensembl gene ENSG00000188596.
Subcellular location: Cytoplasm, cytoskeleton, cilium axoneme
Subcellular location (Human Protein Atlas): Cytokinetic bridge; Microtubules; Primary cilium; Basal body; Cytosol
Gene Ontology:
Biological process: sperm flagellum assembly; cilium assembly; cilium movement involved in cell motility; spermatogenesis
Cellular component: axoneme
Genetic constraint (gnomAD): Loss-of-function variants: 170 observed, 208.1 expected, observed/expected ratio (o/e) 0.82, 90% interval 0.72 to 0.93. The upper end of that interval is the gene's LOEUF score, 0.93, which puts it in group 3 of 6, group 1 being the genes least tolerant of losing a copy. Missense variants: 2,279 observed, 2,434.5 expected, observed/expected ratio (o/e) 0.94, 90% interval 0.9 to 0.97. Synonymous variants: 838 observed, 888.9 expected, observed/expected ratio (o/e) 0.94, 90% interval 0.89 to 1.
Gene-disease validity (ClinGen):
ClinGen rates the evidence that CFAP54 causes each of these diseases.
ciliary dyskinesia, primary, 54 (autosomal recessive): Strong. Any primary ciliary dyskinesia in which the cause of the disease is a mutation in the CFAP54 gene.
Homologues: Orthologues: macaque CFAP54 (96% identical), dog CFAP54 (81% identical), rabbit CFAP54 (80% identical), pig CFAP54 (77% identical), rat Cfap54 (74% identical), guinea pig CFAP54 (73% identical), mouse Cfap54 (73% identical), tropical clawed frog cfap54 (43% identical).
Diseases named in the same sentence as CFAP54 in open-access papers:
CFAP54 is named in the same sentence as 9 diseases in open-access papers, as found by Europe PMC text mining. Sharing a sentence is not in itself a finding about the gene and the disease. The quoted sentences say what the papers report.
male infertility (4 papers, 2017 to 2025). The inability of the male to effect fertilization of an ovum after a specified period of unprotected intercourse. "It is currently not known whether mutations in CFAP52 affect male fertility although mutations in WD-repeat proteins, as e.g. in WDR66/CFAP251, WDR96/CFAP43, and WDR52/CFAP54, causing human male infertility due to the sperm flagella defects have been reported." (PMID 32859975, 2020). "Notably, CFAP54 was initially associated with male infertility due to MMAF and NOA." (PMID 41393159, 2025). "Male infertility is also frequent amongst PCD patients and mouse models deficient for genes involved in the generation or function of motile cilia, such as Poc1a or Cfap54, showed impaired spermatogenesis and male infertility." (PMID 29245899, 2017).
primary ciliary dyskinesia (3 papers, 2020 to 2025). A rare, genetically heterogeneous, primarily respiratory disorder characterized by chronic upper and lower respiratory tract disease. "Mutations in the underlying genes, CFAP54 (C1d) and HYDIN (C2b), lead to symptoms associated with primary ciliary dyskinesia including sperm motility defects." (PMID 32785227, 2020).
Hydrocephalus (2 papers, 2018 to 2019). Hydrocephalus is an active distension of the ventricular system of the brain resulting from inadequate passage of CSF from its point of production within the cerebral ventricles to its point of absorption into the systemic circulation. "The role played by the genetic background for manifestation of hydrocephalus was previously demonstrated in mouse models of PCD lacking ciliary proteins CFAP221, CFAP54 and SPEF2, respectively." (PMID 31383820, 2019). "We previously demonstrated that mouse models of PCD lacking ciliary proteins CFAP221, CFAP54 and SPEF2 all have hydrocephalus with a strain-dependent severity." (PMID 30190587, 2018).
ciliopathy (1 paper, 2022). A genetic disorder of the cellular cilia or the cilia anchoring structures, the basal bodies, or of ciliary function. "CFAP54, NME8, and CFAP46 are ciliopathy-related genes that strongly increase the risk of respiratory infections due to the inability to remove inhaled pathogens, including SARS-CoV-2." (PMID 36552859, 2022).
gliosarcoma (1 paper, 2019). A rare histological variant of glioblastoma (WHO grade IV) characterized by a biphasic tissue pattern with alternating areas displaying glial and mesenchymal differentiation (WHO). "Several mRNAs: MLYCD, CFAP54, ATP9B, and TMEM212 were significantly downregulated in gliosarcomas when compared to GBMs." (PMID 30818875, 2019).
cancer (1 paper, 2024). A tumor composed of atypical neoplastic, often pleomorphic cells that invade other tissues. "In the second family in which MPT21 and two relatives were tested, we found four LP variants (BPIF1, BCORL1, ROPN1, and PRSS3) and four other cancer-related genes (TUBB2B, CFAP54, PSG2, and SIRPB1)." (PMID 39408606, 2024).
CFAP54 also shares sentences with these, for which no sentence is quoted: astrocytomas (1 paper); ependymoma (1); respiratory infections (1).